RET (ret proto-oncogene)
Diseases named in the same sentence as RET in open-access papers (continued):
Sharing a sentence is not in itself a finding about the gene and the disease.
cancer (continued). "Our results underscore the clinical potential of vepafestinib in treating RET-driven cancers." (PMID 37743366, 2023). "Examples of ongoing clinical trials for selpercatinib in RET fusion-positive cancers." (PMID 37360768, 2023). "Another study (LIBRETTO-321; NCT04280081) included Chinese patients with RET-altered cancers." (PMID 37360768, 2023). "Among the 40 cfRNA samples from positive cancer patients, we could identify altered transcripts in 28; including 10 ALK, 6 ROS1, and 7 RET fusion transcripts and 5 MET∆ex14 splicing variants." (PMID 37243883, 2023). "Pathologists have an essential role in shaping clinical practice for RET-altered cancers." (PMID 37277734, 2023). "Findings from this study suggest that 1L selpercatinib use may be more efficacious and more appropriate compared to standard therapies for patients with RET-activated cancers." (PMID 38201566, 2023). "For example, only 1.3% of the total number of analyzed carcinomas demonstrated 5′/3′-end imbalance with a deltaCt >/=3; 152/169 (89.9%) tumors meeting this cut-off carried common RET rearrangements; however, only 152/185 (82.2%) NSCLCs with RET fusions had a deltaCt satisfying this cut-off." (PMID 37445709, 2023). "NCOA4/RET fusion-positive carcinomas were compared with carcinomas harboring other RET fusions." (PMID 37882481, 2023). "The ARROW trial integrated a phase I dose escalation (from 30 to 600 mg once daily) to establish the maximum tolerated dose of pralsetinib, and phase II expansion cohorts (400 mg/daily) enrolling patients with RET-mutant cancers (ClinicalTrials.gov, Identifier NCT03037385)." (PMID 35422765, 2022). "From March 2017 up to July 2020, 521 patients with RET-mutant cancers were enrolled." (PMID 35422765, 2022). "Next-generation TKI assays may require discriminating between RET fusion-positive and RET-mutant cancers, and differences in resistance between selpercatinib and pralsetinib." (PMID 36582799, 2022). "Recently, genetic alterations of RET have been identified in diverse cancer types." (PMID 35268691, 2022). "Vandetanib is the first targeted medication specifically approved by the FDA for the treatment of MTC, acting not only on epidermal growth factor receptor (EGFR), VEGFR, and RET in cancer cells but also inhibiting other TK and serine/threonine kinases and possessing anti-angiogenesis properties." (PMID 36612173, 2022). "Data on RET deletions as driver alterations in cancer are still scarce." (PMID 36091144, 2022). "Targeting chemical kinase inhibitors to tissues with oncogenic RET may offer a viable treatment for RET-dependent cancers." (PMID 36003330, 2022). "It selectively inhibits RET autophosphorylation and proliferation of RET-mutant cancer cells." (PMID 35408658, 2022). "Oncogenic RET alterations confer constitutive activation in multiple cancers." (PMID 35957881, 2022). "To date, only multiple kinase inhibitors are widely used to treat RET-positive cancer patients." (PMID 35268691, 2022). "The comprehensive genetic profiling of tumors made possible by novel detection technologies has resulted in the identification of multiple cancers with rare RET alterations beyond point mutations and fusions, including a nonnegligible number of RET deletions." (PMID 36091144, 2022). "In conclusion, this structural analysis of cysteine-mutant RET ECD suggests a potential key mechanism of cancer induction in MEN2A, both in the absence and presence of its native ligands, and may offer new targets for therapeutic intervention." (PMID 35985422, 2022). "While data is limited for use of cabozantinib in treatment of central nervous system (CNS) tumors, such as BCBM, cabozantinib penetrates the BBB and may prove to be effective in targeting brain malignancies arising from RET-altered cancers." (PMID 35957881, 2022). "The cancers harboring RET alterations, particularly NSCLC, can be treated with pralsetinib." (PMID 35408658, 2022).
cancer (continued). "It is well tolerated and a potential therapeutic for RET-altered cancers." (PMID 36557971, 2022). "Given that aberrant RET activity is an oncogenic driver in numerous cancers, RET is considered an optimal target for therapeutic intervention, first with multi-kinase inhibitors which were soon followed by the first generation of selective RET inhibitors." (PMID 35957881, 2022). "In the past few years, the treatment of RET-altered cancer has mainly focused on MKIs." (PMID 36557971, 2022). "Focal adhesion, cAMP signaling pathways, and pathways in cancer were also under the most upregulated KEGG pathways in PPGLs with EPAS1 mutation compared with tumors bearing a mutation in one of the cluster 2 susceptibility genes (NF1, RET, MAX)." (PMID 35159368, 2022). "In-vitro co-culture of dorsal root ganglia and human pancreatic adenocarcinoma cell lines and in-vivo murine sciatic nerve models of PNI showed that nerves release GDNF, and induce polarized neurotrophic migration of cancer cells via downstream pathways of RET." (PMID 35223829, 2022). "Thus, RET is considered as an important therapeutic target for the treatment of different types of cancer." (PMID 33525725, 2021). "Since several studies have reported that RET activates STAT3 in different types of cancer, CDK5-mediated STAT3 activation with GDNF treatment remains unknown in this study." (PMID 34207842, 2021). "In addition, we identified RET, CBL, and DDR2 driver mutations as potential response markers in hypermutated cancers." (PMID 34503126, 2021). "Alterations in BRAF, RAS, RET/PTC, and TERT promoters are assumed as “driver” changes and could be used as diagnostic markers for cancer development." (PMID 34684168, 2021). "Recently Food and Drug Administration (FDA)-approved pralsetinib (BLU-667) and selpercatinib (LOXO-292) are RET-selective protein tyrosine kinase inhibitors for treating RET-altered cancers, but whether they have distinct activity was unknown." (PMID 34099825, 2021). "RET and TRK mutations are in general mutually exclusive in cancer, with the exception of rare instances in which a secondary TRK mutation may bypass RET inhibition." (PMID 34373541, 2021). "However, at a variance from the in vitro setting, in vivo Pz-1 attenuated growth of RET/TRKA-negative cancer models, as well." (PMID 34373541, 2021). "Dysregulation of RET signaling plays critical role in different human cancers." (PMID 33525725, 2021). "RET, CBL, and DDR2 driver mutations might represent potential response markers in hypermutated cancers." (PMID 34503126, 2021). "Liquid biopsy test reported actionable alterations in ARID1A gene, rearranged during transfection (RET) gene fusions, epidermal growth factor receptor (EGFR) gene R776H mutation, breast cancer (BRCA) genes 1/2, and cyclin-dependent kinase inhibitor 2A (CDKN2A) gene mutations." (PMID 33608032, 2021). "There were more FLT3, FGFR1, and AKT1 mutations (p-value < 0.05) in nonhypermutated cancers, while there were more RET, CBL, and DDR2 mutations (p-value < 0.05) in hypermutated cancers." (PMID 34503126, 2021). "Problem 1 asked participants to predict molecules that bound the RETM955T-associated cancer pro-targets RET[M918T], BRAF, SRC, S6K, and did not bind the anti-targets MKNK1, TTK, ERK8, PDK1, and PAK3." (PMID 34520464, 2021). "RET is commonly activated by gene fusions in different cancers." (PMID 34373541, 2021). "Treatment with regorafenib (RET inhibitor) reduced cancer invasion along neurites, suggesting that GDNF may have a critical role in PNI in head and neck SCC." (PMID 34885121, 2021). "In this light, RET and TRKs represent appealing targets for cancer therapy." (PMID 34373541, 2021).
cancer (continued). "GDF15/GRAL/RET signaling plays an important role in appetite control, and attempts to identify druggable targets in this pathway and develop related novel treatments for obesity or cancer-induced cachexia are ongoing." (PMID 32911810, 2020). "Some multiple TKIs have shown activity in NSCLC with RET fusion, as well as in other cancer types." (PMID 31598903, 2020). "However, the data produced with these inhibitors in cancer cell lines shed little light on the role of RET in oncogenesis." (PMID 32993133, 2020). "Thus, BRAF V600E and RET/PTC confer > 99% probability of cancer, which is consistent with the literature." (PMID 32781560, 2020). "Subsequently, fusion of RET with various other upstream partners were discovered in lung and other cancers." (PMID 33318047, 2020). "Among patients with known cancer staging, 42.9% of those with RET variants and 36.4% of those with negative analysis had locally advanced disease (T > 1)." (PMID 33167350, 2020). "Bioinformatics analyses showed that the expression levels of six out of 25 genes (ERO1B, DPY19L1, NCAM1, RET, MARCH1, and SLC7A8) were associated with LUAD patient survival (p < 0.05), and pathway analyses indicated that major cancer signaling was altered in the subtypes." (PMID 32235589, 2020). "Taking into account that oncogenic mutations can activate RET receptor tyrosinase kinase leading to its direct involvement in different carcinomas, RET inhibition may represent a promising goal for anticancer therapy." (PMID 33217987, 2020). "Importantly, the batch effect causes substantial differences in germline variant distribution patterns across numerous genes, including prominent cancer predisposition genes such as BRCA1, RET, MAX, and KRAS." (PMID 31391007, 2019). "These are representative known cancer predisposition genes: BRCA1, BRCA2, KRAS and RET." (PMID 31391007, 2019). "In NSCLC, several case reports showing clinical activity in RET fusion-positive patients treated with either vandetanib or cabozantinib suggested that RET fusions may be a driver in this cancer type." (PMID 30038711, 2018). "Together, these data suggest that targeting RET may be therapeutically valuable in a broader and more diverse group of human cancers than recognized to date." (PMID 30666215, 2018). "In addition to BCR-ABL, ponatinib inhibits a number of other kinases involved in cancer, including RET (and others such as KIT, fibroblast growth factor receptor, and vascular endothelial growth factor receptor) at low-nanomolar concentrations." (PMID 30038711, 2018). "From variant analysis of 46 cancer susceptibility genes, we identified 7 pathogenic and likely pathogenic germline variants in 7 genes in 7 (8%) of the 87 patients, namely, MUTYH, RET, TSC2, BRCA1, BRCA2, ERCC2 and HRAS." (PMID 29684080, 2018). "Our studies demonstrated that high glucose in vitro might be regarded as an accelerator to increase cancer cell proliferation by enhancing the glial cell line-derived neurotrophic factor (GDNF)/RET or epidermal growth factor (EGF)/EGFR signaling pathways." (PMID 30455857, 2018). "Elevated levels of GFL and RET expression, without mutation, are detected in a subset of several other cancers including: melanoma, glioma, neuroblastoma, seminoma, endometrial, and head and neck cancers and renal cell carcinomas." (PMID 30666215, 2018). "Increasing affordability and throughput of next-generation sequencing technologies have dramatically expanded the volume and reduced the thresholds for genetic testing; RET is included on several multigene cancer panels widely tested in oncology and familial cancer clinics." (PMID 29590403, 2018). "Indeed, male germ-line-selective advantage has previously been described for mutations in other genes involved in cancer (e.g. FGFR2, FGFR3, RET, PTPN11) that cause congenital disorders with paternal age effect." (PMID 28733602, 2017).
cancer (continued). "Following referral to cancer genetics, germline deoxyribose nucleic acid analysis yielded no mutation in the REarranged during Transfection (RET) proto-oncogene." (PMID 29708149, 2017). "As MEN2B-like mutations are considered the major somatic events in sporadic cancer, o a paradoxical discrepancy occurs between the possibly more aggressive clinical course of somatic RET 918-induced cancer and the generally better prognoses in all sporadic cancers." (PMID 28181547, 2017). "Hence, we investigated the relevance of RET‐induced miRNAs for its oncogenic activity in cancer progression." (PMID 28122586, 2017). "Oncogenic gene fusions and activating mutations of RET have been identified and well documented as the driving force of tumorigenesis in several adult cancer types, however, no mutations of RET in NB have been found to date." (PMID 29262623, 2017). "GFRA1 protein released by the microenvironment can promoted may enhance cancer cell PNI through activation of RET." (PMID 27566576, 2016). "These agents may offer greater clinical benefit for patients with RET mutant cancers and widen the scope for the clinical use of RET inhibitors." (PMID 26874741, 2016). "The prognostic function of RET has been found in various cancers." (PMID 27092013, 2016). "The oncogenic activation of the RET gene was detected in various cancers." (PMID 27092013, 2016). "Thus, targeting the chaperone function of HSP90 offers an alternative to direct kinase inhibition for therapeutic intervention in RET driven cancer." (PMID 27429741, 2016). "In existing reports, the uniform prognostic functions of RET were found in other cancers." (PMID 27092013, 2016). "In conclusion, we have identified a type II TKI scaffold, shared by ALW-II-41-27, XMD15-44 and HG-6-63-01, that may be used as novel lead for the development of novel agents for the treatment of cancers harboring oncogenic activation of RET." (PMID 26046350, 2015). "Our observations suggest that SPP86 may be a useful chemical tool for studies on RET signaling in cancer models." (PMID 25409876, 2014). "Furthermore SPP86 is cell permeable and inhibits RET signaling in human cancer cell lines at low concentrations." (PMID 25409876, 2014). "In these cancers, RET activates the ERK/MAPK, the PI3K/AKT/mTOR and the JAK/STAT3 pathways." (PMID 23056499, 2012). "Although no significant increased risk for cancer has been identified in patients with autoimmune thyroid disease, a chromosomal translocation resulting in the formation of the mutant RET/PTC fusion protein links these pathologies." (PMID 18304343, 2008). "In addition, small subsets of PTCs, namely those with papillary growth pattern, may harbor fusions of cancer-related genes, among which RET, NTRK1–3, BRAF, and anaplastic lymphoma kinase (ALK) are the most frequent." (PMID 40540622, 2025). "A retrospective analysis of a pan-cancer cohort of 7517 patients treated with multi-TKIs plus 96 patients treated with RET-Is (pralsetinib, selpercatinib) showed that 15 patients developed CE (12 patients chylothorax, 5 patients CA, 5 both)." (PMID 39199650, 2024). "RET KDD was identified in one case with an unknown cancer type." (PMID 36325957, 2023). "Additionally, anti-RET fusion activity is indiscriminate of fusion partner or CNS involvement, indicating that Pralsetinib may serve as an effective therapy for cancers driven by both RET alterations and by overexpression of the wild-type receptor." (PMID 36918928, 2023). "Additionally, those were inactive against RET gatekeeper mutations, which are not infrequent in patients with RET-altered cancers." (PMID 38118420, 2023). "While the combination of the analysis of 5′/3′-end RET expression imbalance and variant-specific PCR allowed identification of RET translocations in approximately 2% of consecutive NSCLCs, this estimate approached 120/2361 (5.1%) in EGFR/KRAS/ALK/ROS1/BRAF/MET-negative carcinomas." (PMID 37445709, 2023).
cancer (continued). "However aberrations of RET are known to be oncogenic drivers in many types of cancers." (PMID 36358717, 2022). "Using the Ret/MTB doxycycline-inducible mouse transgenic system, we show that sustained expression of RET in the mammary epithelium during the post-lactation transition to involution is accompanied by alterations in tissue remodeling and an enhancement of cancer potential." (PMID 35044452, 2022). "We propose that Stat3 activation downstream of persistent RET signaling unleashes apoptosis, accelerating the involution process, and could simultaneously increase inflammation, culminating in chronic Stat3 activation-promoting cancer." (PMID 35044452, 2022). "However, neither the patient’s age nor cancer stage at diagnosis was directly associated with RET fusion types in baseline or secondary patients." (PMID 36059009, 2022). "Having analyzed the prevalence of pathogenic/likely pathogenic germline variants in cancer-predisposition genes in 334 HCC patients considered for liver transplantation, we found only 7/334 (2.1%) carriers of pathogenic variants in established cancer-predisposition genes (PMS2, 4×NBN, FH or RET)." (PMID 36612198, 2022). "Thus, RET represents an ideal actionable oncoprotein and its highly selective inhibition could be effective in the treatment of many cancers." (PMID 35422765, 2022). "Hence, RET is an important therapeutic target for cancer drug design." (PMID 33525725, 2021). "Thus, the Pz-1 inhibitory profile suggested that it may prove useful in cancer driven either by RET or TRKA." (PMID 34373541, 2021). "It was found that BRAF V600E, RET/PTC1 and TERT mutations were associated with aggressive characteristics, whereas BRAF K601E, HRAS, NRAS, KRAS, PAX8-PPARy mutations and tumors with no mutations are significantly less likely to be associated with high risk cancers." (PMID 33910629, 2021). "The prevalence of RET/PTC rearrangements in PTCs varies dramatically in reported series of patients, which is likely due to the heterogeneous distribution of this rearrangement within the carcinoma tissues and the diverse sensitivities associated with the detection methods." (PMID 33669363, 2021). "Moreover, 31 inhibited cell proliferation with a similar potency for BaF3/CCDC6-RET cells and gatekeeper mutant V804 M-driven cell proliferation (IC50 value around 400 nM) highlighting that it could be active against both these RET-driven cancer cells." (PMID 33217987, 2020). "MiR-182 could promote cancer invasion by linking RET oncogene activated NF-κB." (PMID 32541092, 2020). "In addition, cancer subtype specific patterns of COX4 expression were demonstrated, suggesting a role for oxidative phosphorylation in metastatic progression of MTCs, specifically in MTCs harboring RET mutations." (PMID 32911610, 2020). "However, disturbances in cellular levels of RET and GFRɑ co-receptors can lead to undesirable consequences, such as RET activation in the absence of a ligand, which can potentially result in the formation of malignant tumors." (PMID 32993133, 2020). "Taking into account clinical features and genetic test results shows that wild-type RET patients and carriers of MOD risk level variants only differ by family history (p < 0.001), but not by clinical characteristics such as mean age at diagnosis of MTC and cancer stage." (PMID 33167350, 2020). "Moreover, RET seems to also play a role in many other cancer entities and cancer syndromes." (PMID 30621641, 2019). "However, little is known about the role of ATF4 or HSPA5 in the RET signalling pathway in cancer." (PMID 31534554, 2019).